PMS2 (PMS1 homolog 2, mismatch repair system component)
Diseases named in the same sentence as PMS2 in open-access papers (continued):
Sharing a sentence is not in itself a finding about the gene and the disease.
breast carcinoma (continued). "It is not until recently that the link between MSH6, PMS2, and breast cancers started to be comprehensively characterized." (PMID 30630526, 2019). "The spectrum of mutations in the NZBR lines is similar to that found in commonly used breast cancer cell lines, except that the EVI2B, LRP1B and PMS2 mutations have not been reported in breast cancer lines." (PMID 30370249, 2018). "No studies evaluating the predictive value of PMS2 in breast cancer chemotherapy have been done yet and in the present study an inverse relationship was observed between H-score of PMS2 and response to CAF regimen chemotherapy." (PMID 17394628, 2007). "While MLH1 and PMS2 (MutLα complex) also play a key role in the downstream repair steps, we chose to concentrate on the MutSα dimer given the lack of data regarding its expression in breast cancer tissues and its central role in mismatch recognition." (PMID 41283256, 2025). "No studies evaluating the predictive value of PMS2 in breast cancer chemotherapy has been done yet." (PMID 17394628, 2007). "Conversely, some of the detected regions in the present work are not strongly related to breast cancer; recurrent losses affecting 7p22 (segment encompassing, among others, the PMS2 gene) and 5q11-q13 (ERCC8 and XRCC4) could suggest the involvement of DNA repair pathways in cancer progression." (PMID 25391423, 2015). "This lack of correlation between MMR dysfunction and MSI could be due to involvement of MMR genes not leading to MSI formation like MLH6 or PMS2.Thus in breast cancers immunohistochemistry for MMR protein products would appear to be more logical for detection of loss of MMR function." (PMID 17394628, 2007).
ovarian carcinoma (74 papers, 2006 to 2026). A malignant neoplasm originating from the surface ovarian epithelium. "Subclonal mutations in PMS2 are associated with adverse outcomes in rectal and ovarian cancer, while patients with clonal mutations have survival benefits (P-value = 3e−04 and P-value = 1.2e−04, respectively)." (PMID 35962343, 2022). "The two PMS2 mutations are associated with a significantly increased risk of endometrial, colorectal and ovarian cancer, although the overall cancer risks are lower than for the MSH6 mutation." (PMID 28466842, 2017). "We discover a translocation disrupting MLH1 and three mutations in MSH6 and PMS2 that increase endometrial, colorectal, brain and ovarian cancer risk." (PMID 28466842, 2017). "Additionally, she was also counseled that the history of ovarian cancer was more likely to be unrelated to the PMS2 mutation if there was papillary serous histology vs. endometrioid." (PMID 26484312, 2015). "Among seven MMR genes, high mRNA levels of MSH6, MLH1 and PMS2 were significantly associated with a better overall survival for all ovarian cancer patients treated with platinum-based chemotherapy, especially in late-stage and poor-differentiated ovarian cancer patients." (PMID 29063235, 2018). "Several oncogenes frequently mutated in endometrial and ovarian cancer (ARID1B, ATM, BRCA1, CHD2, POLE, and PMS2) were also present in LMS." (PMID 39691991, 2025). "Concurrent pathogenic germline mutations in MLH1, PMS2, and MUTYH were found in three patients (two in uterine cancer and one in ovarian cancer)." (PMID 37310942, 2023). "PV in 10 PDAC patients with multiple primary tumors affected 3 × BRCA1 and 4 × BRCA2 (all had also developed breast and/or ovarian cancer), 1 × PMS2 and 1 × MLH1/MSH6 (both developed colon cancer), and 1 × CDKN2A (diagnosed with melanoma)." (PMID 34503238, 2021). "Rs7797466 was the most studied SNP of PMS2 and found to be associated with increasing risk of pancreatic, CRC and ovarian cancer." (PMID 32756484, 2020).
ovarian carcinoma (continued). "Increased MSH6 and MLH1 mRNA levels were associated with a better OS in stage III + IV ovarian cancer patients, high mRNA levels of PMS2 implied an improved OS either in stage I + II or stage III + IV ovarian cancer patients." (PMID 29063235, 2018). "There is little evidence to suggest an increased risk of ovarian cancer in women with pathogenic variants in PMS2." (PMID 41214301, 2026). "Data from the Prospective Lynch Syndrome Database indicate that individuals carrying heterozygous pathogenic PMS2 variants do not exhibit an elevated risk of developing colorectal, endometrial, or ovarian cancer prior to the age of 50." (PMID 39768893, 2024). "In contrast, updated evidence in MSH6 and PMS2 carriers does not show a definitive increased lifetime risk of ovarian cancer, which is different from broader non-variant risk estimates utilized in the past." (PMID 36937421, 2023). "Our results showed that high mRNA levels of MSH6, MLH1, and PMS2 were associated with a favorable OS in ovarian cancer, suggesting these MMR genes may serve as potential positive prognostic indicators in ovarian cancer patients treated with platinum-based chemotherapy." (PMID 29063235, 2018). "On the other hand, ATM and PALB2 are considered moderate penetrance genes in breast and ovarian cancer, and MSH6, PMS2, and EPCAM are considered moderate penetrance genes in LS CRC." (PMID 38201484, 2023). "We found that 8 of our 93 regions contained such types of genes, nine in total, including AKT1, ARNT, PMS2, and the oncogenic ubiquitin hydrolase, DUB3 for which we previously reported abnormal demethylation in our integrated study of ovarian cancer." (PMID 23293768, 2012). "While high levels of MLH1 were associated with a better OS in grade III ovarian cancers and increased mRNA expression of PMS2 was positively correlated with OS in grade II ovarian cancer, MSH6 mRNA expression was a favorable predictor of OS both in grade II and grade III ovarian cancer patients." (PMID 29063235, 2018). "Immunohistochemistry of the bowel tumor showed loss of PMS2; MSI was also demonstrated, leading to diagnostic sequencing of PMS2, although there was no family history of neoplasia other than an ovarian cancer in a second-degree relative after age 70 years." (PMID 29909963, 2018). "In addition, our study showed the expression of MSH6, MLH1 and PMS2 gene exerted positive influences on OS of late-stage and poor-differentiated ovarian cancer patients, but not of early stage and well-differentiated ovarian cancer patients." (PMID 29063235, 2018).
hereditary non-polyposis colorectal cancer (55 papers, 2006 to 2026). "Germ-line mutation and loss of PMS2 is associated with Turcot's syndrome (TS), a variant of hereditary non-polyposis colorectal cancer (HNPCC) syndrome, characterised by colonic polyposis and brain tumours." (PMID 25026297, 2014). "For example, Mlh1 is known to interact with Pms2, both of which are well-studied DNA mismatch repair genes frequently mutated in hereditary nonpolyposis colorectal cancer." (PMID 25502805, 2014). "Further evaluation regarding the consequence of PMS2 c.2186_2187del seems necessary, given the gene's relevance to HBOC, hereditary nonpolyposis colon cancer, and constitutional mismatch repair deficiency syndrome." (PMID 39126233, 2024).
hereditary non-polyposis colorectal cancer (continued). "Lynch syndrome (LS; also called hereditary nonpolyposis colorectal cancer, HNPCC) is a hereditary cancer susceptibility/predisposition disease caused by a heterozygous germ line mutation in the DNA mismatch repair (MMR) gene MSH2MSH6MLH1 or PMS2." (PMID 22824075, 2012).